FGFR3 (fibroblast growth factor receptor 3)
Diseases named in the same sentence as FGFR3 in open-access papers (continued):
Sharing a sentence is not in itself a finding about the gene and the disease.
bladder tumors (57 papers, 2005 to 2025). "It has also been demonstrated that FGFR3 expression follows the distribution of FGFR3 mutations, with significantly higher levels of expression in low stage and grade bladder tumors than in invasive carcinomas." (PMID 39031286, 2024). "It has been reported that the FGFR3 and CK20 were efficient prognostic factors of pTa bladder tumors, since it can distinguish the differentiated tumors with FGFR3 mutations." (PMID 32795296, 2020). "FGFR3 mutations are more common in pTa bladder tumors, less regular in pT1G3 tumors, and rare in carcinoma in situ (pTis)." (PMID 32795296, 2020). "It has been suggested that this overexpression is also mediated by a loss of microRNAs99/100 targeting FGFR3 in bladder tumors." (PMID 29463565, 2018). "In contrast, a lysine‐to‐glutamic acid substitution, K650E, in the kinase domain of FGFR3, found in a small number of bladder tumours (∼1% of all mutations), exaggerates ligand‐dependent kinase activation." (PMID 30043421, 2018). "Consistently, we found that human bladder tumors bearing FGFR3 mutations had levels of FGFR3 and MYC expression that were positively correlated." (PMID 29463565, 2018). "In this study, we investigated the molecular mechanisms underlying the oncogenic activity of activated FGFR3 in bladder tumors, with a view to identifying new drug targets to improve treatment efficacy and/or limit resistance." (PMID 29463565, 2018). "Mutations are, by far, the most frequent alterations of FGFR3, occurring in almost 50% of bladder tumors (70% of NMIBCs and 15–20% of MIBCs)." (PMID 29463565, 2018). "Among patients who had a bladder tumor confirmed at histopathologic examination, urine DNA was positive for at least one of the tested biomarkers (FGFR3 mutations and promoter hypermethylation events) in 94% of cases." (PMID 26151138, 2015). "In contrast to the high prevalence of FGFR3 mutations in urine from patients with confirmed bladder tumor (67%), only one of the patients with benign histopathology had a FGFR3 mutation detectable in urine." (PMID 26151138, 2015). "FGFR3 is implicated as an oncogene in the majority (~80%) of low-grade non-invasive (stage Ta) bladder tumors and ~40% of invasive bladder tumors." (PMID 24944696, 2014). "It is well-known that FGFR3 mutations occur predominantly in bladder tumours with papillary growth pattern." (PMID 24650297, 2014). "Abnormal activation of the fibroblast growth factor receptor 3 gene (FGFR3) by means of either overexpression or mutation is cited in approximately 80% of non-invasive bladder tumors." (PMID 24298280, 2013). "Beside FGFR3 mutation, two other molecular markers can be used to distinguish the two pathways of bladder tumor progression: the Cis signature and the MRES (multiple regional epigenetic silencing) phenotype." (PMID 22724020, 2012). "One of the most promising markers associated with NMI bladder tumors is the mutation status of the Fibroblast Growth Factor Receptor-3 (FGFR3)." (PMID 20187926, 2010). "This suggests that screening bladder tumors for mutations in genes such as FGFR3, RAS and PIK3CA can be of importance for future therapy decisions." (PMID 21072204, 2010).
bladder tumors (continued). "Mutations in the FGFR3 gene have been identified in 40–50% of bladder tumours, and were associated with a favourable prognosis with a lower recurrence rate and disease-specific mortality." (PMID 17088904, 2006). "FGFR3 mutations may potentially affect bladder tumor recurrence in UTUC (OR, 11.00; 95% CI, 0.96–125.77; p = 0.054); however, the result was not statistically significant." (PMID 38592174, 2024). "While bladder tumors with a luminal subtype and/or FGFR3 mutations have both been associated with a non–T cell–inflamed tumor microenvironment, whether FGFR3 alterations functionally mediate this non–T cell–inflamed phenotype has not been directly explored." (PMID 38226620, 2024). "Consequently, FGFR3 mutations are commonly found in the papillary and luminal subtypes of bladder tumors." (PMID 37153545, 2023). "The FGFR3 gene may affect tumorigenesis even before gene translation: the circRNA product of FGFR3 gene transcription—has_circ_0068871 is overexpressed in bladder tumors and linked to tumor cell proliferation and migration." (PMID 35991125, 2022). "In addition, studies have shown that FGFR3 mutations occur in 50% of primary bladder tumors and are associated with a favorable prognosis." (PMID 34532318, 2021). "FGFR3 excessive gene mutation and protein expression were first discovered in bladder tumor." (PMID 33381388, 2020). "These cell lines were derived from human bladder tumors, and they endogenously express a mutated activated form of FGFR3 (FGFR3‐Y375C, the second most frequent mutation in bladder tumors) and the FGFR3‐TACC3 fusion protein (the most frequent FGFR3 fusion protein in bladder tumors), respectively." (PMID 29463565, 2018). "We looked for other ways to disrupt the FGFR3/MYC loop in bladder tumors bearing FGFR3 mutations." (PMID 29463565, 2018). "We also asked whether FGFR3 mutation could occur at earlier stages of cervical tumor progression, like in bladder tumors for which the highest rate of mutation is for low-stage non invasive pTa tumors." (PMID 15869706, 2005). "Previous studies have shown that FGFR3 mutations are encountered more frequently in luminal tumors, which are known to be comparatively less responsive to checkpoint inhibition, and that FGFR3-mutated bladder tumors are associated with decreased T-cell infiltration and low PD-L1 expression." (PMID 36601039, 2022). "As FGFR3 mutations are more common in low grade and stage bladder tumours, and are an early change during urothelial transformation, it is likely that besides favouring EMT in more advanced tumours, ETV5 may modulate other classes of genes in early neoplastic lesions." (PMID 30952872, 2019). "Interestingly, studies of MYC mRNA levels and of the phosphorylation of p38 and AKT in human bladder tumor samples harboring FGFR3 mutations suggested that this loop might also operate in tumors." (PMID 29463565, 2018). "As mutations of FGFR3 are found in up to 80% of primary Ta tumours, which are characterized by a high recurrence rate, detection of FGFR3 mutations in urine is currently under study as a noninvasive and inexpensive method for the surveillance of superficial FGFR3 mutation-positive bladder tumours." (PMID 22899908, 2012). "Turo et al39 used immunohistochemistry to compare FGFR3 expression in matched primary bladder tumors and lymph node metastases in 150 patients." (PMID 41097827, 2025). "The functioning of daidzein in contrast to bladder tumor was impaired by the knockdown of endogenous FGFR3, indicating that the expression of daidzein was primarily modulated by the FGFR3 pathway." (PMID 40078339, 2025). "FGFR inhibition cooperates with PD-1 checkpoint blockade to reverse anti-PD-1 induced Treg expansion and block progression of murine FGFR3-mutant bladder tumors." (PMID 38226620, 2024). "Low-grade high-PD-L1(+) double-negative recurrent noninvasive bladder carcinoma was characterized by a higher FGFR3 expression than that of high-grade bladder tumor." (PMID 34576020, 2021).
bladder tumors (continued). "Overall this study advances our understanding of the molecular alterations occurring during urothelial malignant transformation and indicates TAZ as a possible therapeutic target in FGFR3-dependent bladder tumours." (PMID 30952872, 2019). "We demonstrated that JQ1 prevented BRD4 binding to the MYC promoter and enhancer, thereby inhibiting MYC expression and, consequently, the growth of bladder tumor cells expressing activated forms of FGFR3 both in vitro and in vivo in xenograft." (PMID 29463565, 2018). "Together, these findings highlight the critical role of FGFR3 in bladder tumor carcinogenesis, raising the possibility of developing anti‐FGFR3 therapies for both NMIBC and MIBC." (PMID 29463565, 2018). "To this end, we considered the case of activating mutations of fibroblast growth factor receptor 3 (FGFR3) and of the oncogene PI3K, one of the co-occurrent genetic perturbations observed in bladder tumors." (PMID 30245634, 2018). "In light of its key role downstream from FGFR, MYC inhibition appears to be a valuable therapeutic strategy for bladder tumors with FGFR3 alterations." (PMID 29463565, 2018). "Overall, FGFR3 and Ki67 protein expression was analyzed by immunohistochemistry in n = 142 primary bladder tumors comprising n = 82 papillary non-invasive tumors (for cohort characteristics)." (PMID 30154342, 2018). "Based on the results presented here, we devised a model for this newly identified FGFR3/MYC positive feedback loop involved in bladder tumor cell proliferation (Graphical abstract)." (PMID 29463565, 2018). "FGFR3 is overexpressed in about 50% of oral squamous cell carcinoma, in the early stage of non-small cell lung cancers, and in bladder tumors." (PMID 30577533, 2018). "In this study, we characterized further the mechanisms involved in the activity of aberrantly activated FGFR3, highlighting new possibilities for the treatment of bladder tumors with activating alterations of FGFR3." (PMID 29463565, 2018). "Mutations in human TERT, FGFR3, PIK3CA, and RAS genes have been proposed as potential molecular markers in bladder tumor." (PMID 27611947, 2016). "By analyzing a broad range of tumors, representative of UBC diversity, we find that ARID1A alterations generally occur in FGFR3 wild type, poor-prognosis bladder tumors." (PMID 23650517, 2013). "Activating mutations in the fibroblast growth factor receptor 3 (FGFR3) occur in >50% of low-grade and low-stage bladder tumors (about 64–85% of pTa tumors carry FGFR3 mutations)." (PMID 22873290, 2012). "With the RAS-BC assay and mutation assays for FGFR3 and PIK3CA, we screened primary bladder tumors of 257 patients for mutations." (PMID 21072204, 2010). "FGFR3 targeted therapy is being considered for muscle-invasive bladder tumors and recently a Phase II study has initiated in patients with advanced urothelial cancer (NCT00790426)." (PMID 21072204, 2010). "With this assay and mutation assays for the FGFR3 and PIK3CA oncogenes, we screened primary bladder tumors of 257 patients and 184 recurrences from 54 patients." (PMID 21072204, 2010). "Therefore, the UPFL1 and UPFL3 cell lines are relevant models for the effects of FGFR3 inhibition in bladder tumors." (PMID 38226620, 2024). "The FGFR3-driven murine bladder tumors reflect their counterparts found in human UC." (PMID 38226620, 2024). "These preclinical results suggest that bladder tumors with FGFR3 alterations could potentially be treated with BET bromodomain inhibitors." (PMID 29463565, 2018).
bladder tumors (continued). "Bladder tumors not enriched for APOBEC mutagenesis are more likely to have mutations in FGFR3 and the RAS family of oncogenes, which are mutually exclusive, and these patients have poor overall survival." (PMID 29435122, 2018). "We have identified a novel FGFR3‐MYC positive feedback loop in bladder tumor cell lines harboring aberrantly activated FGFR3, which may be of clinical relevance, because it was also found in a PDX model harboring an FGFR3 mutation." (PMID 29463565, 2018). "These tumors might also benefit from the alternative therapeutic strategies proposed in this study for bladder tumors displaying aberrant FGFR3 activation." (PMID 29463565, 2018). "Our results thus suggest alternative strategies targeting different aspects of FGFR3 signaling that might be beneficial for the treatment of bladder tumors expressing aberrantly activated FGFR3." (PMID 29463565, 2018). "The activation of p38 by activated‐FGFR3 in bladder tumors contributes to malignant behavior and the inhibition of this activation may be of therapeutic value, as reported for an increasing number of cancers." (PMID 29463565, 2018). "Furthermore, another line of research has interpreted the role of FGFR3 in bladder tumours." (PMID 39107713, 2024). "However, evidence that FGFR3 pathways work in opposition to immune activity is not uniform: FGFR3 amplifications are associated with decreased anti-inflammatory M2 macrophage bladder tumor infiltration." (PMID 33224141, 2020). "Moreover, MYC expression was positively correlated with FGFR3 expression in bladder tumors harboring a mutated FGFR3, whereas no such correlation was observed in tumors bearing wild‐type FGFR3 (n = 122)." (PMID 29463565, 2018). "A relevance of this loop to human bladder tumors was supported by the positive correlation between FGFR3 and MYC levels in tumors bearing FGFR3 mutations, and the decrease in FGFR3 and MYC levels following anti‐FGFR treatment in a PDX model bearing an FGFR3 mutation." (PMID 29463565, 2018). "This could be related to a specific FGFR3‐induced MYC transcriptomic program in bladder tumors." (PMID 29463565, 2018). "Hence, our comprehensive study provides novel insights into a subgroup of squamous differentiated bladder tumors that hold clues for novel therapeutic regimens and may benefit from FGFR3-targeted therapies." (PMID 27669755, 2016). "Our scRNA-seq studies demonstrate that FGFR3 promotes luminal expression patterns across all urothelial cell types, verifying that FGFR inhibition has the ability to affect the majority of bladder tumor cells." (PMID 38226620, 2024). "Together, these results demonstrate that FGFR3 activation can drive RNA expression patterns that reflect UROMOL class 1 and consensus LumP bladder tumor subtypes, both of which have relatively good prognosis." (PMID 38226620, 2024). "In the FGFR3-mutant MGHU3 and UMUC14 lines, which are derived from less invasive bladder tumours, ETV5 knockdown had a similar effect on reducing cell numbers at confluence, but a less striking effect on colony formation." (PMID 30952872, 2019). "To investigate the link between FGFR3, ETV5 and TAZ in vivo we interrogated two large publically available bladder tumour data sets." (PMID 30952872, 2019).
bladder tumors (continued). "Using RT112 and MGH‐U3 xenograft models treated for 9 days with a pan‐FGFR inhibitor, PD173074, which delayed tumor growth, we also showed in vivo that FGFR3 and MYC were involved in a positive feedback circuit inducing bladder tumor growth." (PMID 29463565, 2018). "The identification of the appropriate subset(s) of UBC patients who will benefit most from FGFR-directed therapy is a significant challenge as not all patients with FGFR3 mutated bladder tumors respond to FGFR inhibition, and there are also responders without FGFR3 alterations." (PMID 39031286, 2024). "However, we did not study the impact of ERK1/2 inactivation in our FGFR3‐dependent bladder tumor models and we cannot, therefore, rule out the possible involvement of this pathway in cooperation with the AKT pathway, as shown for RAS." (PMID 29463565, 2018).